IL17F (interleukin 17F)
Diseases named in the same sentence as IL17F in open-access papers (continued):
Sharing a sentence is not in itself a finding about the gene and the disease.
infection (continued). "T helper 17 cells (CD4-positive [CD4+] IL-17A+ and CD4+ IL-17F+), IL-17A- and IL-17F-producing CD8+ T cells, IL-17A-producing γδ T cells, and IL-17A-producing innate lymphoid cells (ILCs) were significantly increased in the skin samples 14 days after infection." (PMID 36695588, 2023). "Nevertheless, we cannot exclude the potential contribution of IL17F production by other cell populations at the site of the infection that were not analyzed in this study, so further studies would be required to confirm our hypothesis." (PMID 31616423, 2019). "IL-17A and IL-17F act on many non-immune cells, including epithelial cells, inducing: (i) production of chemokines that in turn mobilize and recruit neutrophils and macrophages to the site of infection; and (ii) production of anti-microbial peptides." (PMID 26812180, 2016). "Interestingly, a significant induction (8 to 28 fold) of IL-22, IL-17A and IL-17F was also observed for the avirulent strain, while induction of the eight next most expressed cytokines during infection with the virulent strain were either not induced or induced weakly (<2-fold)." (PMID 22675469, 2012).
tumor (66 papers, 2012 to 2025). "Recently, the potential of IL-17F to inhibit the formation of vasculogenic mimicry structures, an alternative vasculogenic system made by aggressive tumor cells implicated in treatment failure and poor survival of cancer patients, was reported." (PMID 37373022, 2023). "Polymorphisms of IL-17 and IL-17F have been associated with oral squamous cell carcinoma risk, and are related to tumor stage and differentiation, and potentiate the protumorogenic effects of tobacco and alcohol, enhancing thus the risk of OSCC development." (PMID 37373022, 2023). "Most cells derived extracellular IL-17F at the tumor invasion front, which was associated with better disease-specific survival among patients with all stages oral tongue squamous cell carcinoma." (PMID 37373022, 2023). "Contrariwise, IL-17F plays a protective role in colon tumorigenesis because IL-17F-deficient mice show an enhanced tumor development, notably with a downregulated angiogenesis in vivo." (PMID 35626056, 2022). "Extracellular IL-17F at the tumour invasion front was associated with better disease-specific survival among oral tongue squamous cell carcinoma (OTSCC) patients." (PMID 35012470, 2022). "It seems that despite operating through the same receptor, IL-17A and IL-17F cause contradictory effects on tumor progression." (PMID 35884974, 2022). "Tc17 cells (characterised by IL-17A, IL-17F, IL-21, IL-22 production and low levels of granzyme B) have been associated with both anti-tumour (esophageal SCC patients) and pro-tumour activity (HNSCC patients)." (PMID 35406451, 2022). "Inflammatory Th17 cells and their associated cytokines (i.e., IL-17A, IL-17F, IL-21, IL-22, etc.)mediate tumor growth in two distinct ways – by driving angiogenesis and by suppressing antitumor immunity." (PMID 24987392, 2014). "Additionally, IL-17F suppressed cancer associated fibroblasts mediated invasion of oral tongue squamous carcinoma cells in tumor spheroids." (PMID 37373022, 2023). "Such paradoxical effects were previously reported in other cases such as IL-17F deficiency, and may possibly be attributed to the common function of Gal2 in promoting cell death under oxidative stress in both epithelial cells and tumor cells." (PMID 33110234, 2021). "Our data indicate that Tc17 cells highly express a range of cytokines, notably IL-16, IL-17A, IL-17F, IL-22, and IL-26, and it is these five cytokines for which receptors are also highly expressed in tumor cells." (PMID 40452847, 2025). "There were notable differences in baseline cytokine levels based on primary tumor histology, particularly involving IL-8, IL-17f, IP-10, and RANTES." (PMID 39403930, 2024). "In contrast, IL-17F has a tumor suppressive effect in CRC, possibly by inhibiting tumor angiogenesis, and Il17a- and Il17f-deficient mice develop fewer and more tumors, respectively, compared to littermate controls in the AOM/DSS model." (PMID 38500875, 2024). "The extracellular MC-derived IL-17F at the tumor invasion front of oral tongue squamous cell carcinoma was associated with better disease-specific survival." (PMID 39064602, 2024). "On the other hand, Th17 cells inhibit tumor angiogenesis by secreting TNF-α, IFN-γ, IL-17F, IL-21 and IL-22, which inhibit tumor growth and promote the apoptosis of cancer cells." (PMID 39534095, 2024). "IL-17A, IL-17F, and IL-22 display anti-tumor effects in CRC, aiding immune cell recruitment, tissue repair, and reducing inflammation and angiogenesis-promoting factors." (PMID 38415252, 2024). "Given the role of Th17 and Th22 cells in promoting tumor development, IL-17A, IL-17F, and IL-22 are also promising targets in CRC." (PMID 38918278, 2024). "Additional studies indicate that the genetic deletion of either IL-17A or IL-17F can also impede tumor development in APCMin tumor mice." (PMID 39906741, 2024).
tumor (continued). "We validated the upregulation of Il17a, Il17f, Havcr2, and Areg at protein level in Vγ4+ and Vγ6+ cells from the lungs of WT and tumor-bearing KB1P mice by flow cytometry." (PMID 36480166, 2023). "Human CRC samples show lower levels of IL-17F messenger RNA and IL-17F protein than non-tumor tissues from the same patient." (PMID 38137417, 2023). "Interleukin 17A and IL-17F polymorphisms are associated with increased risk for OSCC and are related to tumor stage and differentiation." (PMID 37373022, 2023). "To summarize, IL-17F expression (protein and mRNA) levels in tumour and serum samples seem to depend on cancer type, and more studies are needed prior to concluding its predictive value in any of the malignancies." (PMID 35012470, 2022). "Accordingly, an in vivo study shows that IL-17F suppresses the tumor growth in mice bearing the hepatocarcinoma cell line SMMC-7721." (PMID 35626056, 2022). "Tong and his colleagues claimed an anti-tumorigenic role for IL-17F by showing a significant decrease in the tumor growth when IL-17F over expressed HCT116 cells transplanted subcutaneously in nude mice comparing with the mock transfectants." (PMID 35012470, 2022). "Data on the protective role of IL-17F in tumor progression due to inhibition of angiogenesis have been published, and its overproduction leads to a reduction in tumor formation in the colon (shown in mouse and human models)." (PMID 36422171, 2022). "The results have varied in different cancers and depending on the expression (protein or mRNA) and location (tumour tissue or soluble) of IL-17F." (PMID 35012470, 2022). "Several mechanisms have been suggested through which IL-17F exert its antitumorigenic effects, including inhibition of tumour angiogenesis, cell cycle regulation, cancer cell proliferation and migration, and cancer vasculogenic mimicry." (PMID 35012470, 2022). "Given the roles of Th17 and Th22 cells in promoting tumor development, IL-17A, IL-17F, and IL-22 are also promising targets in CRC." (PMID 34489941, 2021). "We evaluated the plasma concentrations of Th1 (IL-2, IFN-γ, and TNF-α), Th2 (IL-4, IL-5, IL-6, and IL-10), Th9 (IL-9), and Th17 (IL-17A, IL-17F, IL-21, and IL-22) cytokines in tumor-bearing mice by flow cytometry." (PMID 32802733, 2020). "In this study, IL-17F was also proved to have the tumour suppression effect in CC possibly by inhibiting tumour angiogenesis." (PMID 32760201, 2020). "While IL-17D and IL-17E appear to exert preponderant tumor-protective activities, IL-17B, IL-17C, and IL-17F are tumor promoting, either through a direct effect on tumor cells, or by modulating the tumor microenvironment." (PMID 33244315, 2020). "Because IL-17F can be tumor promoting, it will be interesting to investigate the anti-tumor activity of Bimekizumab especially in colorectal cancer." (PMID 33244315, 2020). "TH17 cells, on the other hand, produce IL-17A, IL-17F, IL-21, and IL-22, which promote tumor growth by favoring antimicrobial tissue inflammation." (PMID 31906017, 2019). "In the present study, we found that IL-17F was elevated in patients with HCV and advanced fibrosis and that IL-17F mRNA was also elevated in HCV-associated tumor tissue." (PMID 28770001, 2017). "In a heterotopic tumor model where HCT 116 CRC cells were engineered to overexpress IL-17F, tumor growth was inhibited likely through inhibition of angiogenesis." (PMID 27148488, 2016). "Yet, other cytokines secreted by Th17 cells (IL-17F, IL-21, and IL-22) exhibit anti-angiogenic properties, convoluting the overall correlation between Th17 cell activity and tumor growth in the context of angiogenesis." (PMID 24987392, 2014). "At 3 weeks after transplantation, the mean tumor weights of 0.026 g, 0.023 g, 0.036 g were found in three different IL-17F-transfected tumors, and 0.062 g in wild-type tumors." (PMID 22509371, 2012). "The inhibition of IL-17F on the endothelial angiogenesis prompted us to examine the tumor angiogenesis." (PMID 22509371, 2012).
tumor (continued). "One possible explanation is that another cell in the tumor microenvironments was regulated by IL-17F/IL-17A in production of VEGF." (PMID 22509371, 2012). "Since IL-17F is an important effecter of Th17 cells, the mechanism involved in our current study is probably a host-depended tumor growth inhibiting effects induced by IL-17F." (PMID 22509371, 2012). "The enhanced tumor formation in Il-17f−/− mice was consistent with inhibited tumor growth by IL-17F over-expression, together revealed an inhibitory role for IL-17F in colon tumorigenesis in vivo." (PMID 22509371, 2012). "While IL-17A is largely associated with tumor progression and metastasis—especially in the aggressive CMS4 subtype—IL-17F may exhibit anti-tumor activity in early-stage CRC by supporting cytotoxic T cell function." (PMID 41244711, 2025). "Depletion of Il17a or Il17f reduces tumor development in APC-driven mouse models of CRC." (PMID 38918278, 2024). "Through our integrated clinical-biomarker–immunologic analyses derived from a diverse, pan-tumor cohort, we found that early increases in Th17 (IL-6, IL-17f), type 2 (IL-5, IL-13, IL-25), and type 1 (TNF-α) cytokines were associated with the development of grade ≥ 2 irAEs." (PMID 39403935, 2024). "Interestingly, IL-17A has a dual role in tumor development, whereas IL-17F exhibits tumor-suppressing properties." (PMID 38415252, 2024). "Moreover, acute-phase response signaling, the role of IL-17F in allergic inflammatory airway diseases, and the tumor microenvironment were activated for all CNTs." (PMID 36985953, 2023). "In addition, many studies have demonstrated the overexpression (at mRNA and functional protein levels) of the cytokines IL-17A, IL-17F, IL-21 and IL-22 in the tumor nest in patients with CRC compared to nearby unaffected intestinal mucosa." (PMID 36422171, 2022). "In addition, there was a slight and statistically insignificant correlation with stemness indices and tumor purity in both IL-25 and IL-17F." (PMID 36159856, 2022). "In three articles, IL-17F expression in tumour sections was decreased." (PMID 35012470, 2022). "IL-17F inhibited tumour angiogenesis in three cancer types: liver, colon, and oral." (PMID 35012470, 2022). "Deletion of Il17a or Il17f reduces tumor development in an APC-driven mouse model of CRC." (PMID 34489941, 2021). "Among them, the expression levels of IL-17a and IL-17f are related to tumor angiogenesis." (PMID 32522267, 2020). "Since the Th17 cell subset is a major cellular source of IL-17A and IL-17F, we hypothesized that the downregulation of these two cytokines was related to the number of Th17 cells in tumor tissue." (PMID 33102239, 2020). "CAFs promoted OTSCC invasion in tumor spheroids, whereas IL-17F eliminated such effect." (PMID 31083515, 2019). "Due to its downregulation in tumor cells and inhibitory activity in in vitro cancer models, targeting IL-17F or its regulatory pathways could lead to promising immunotherapeutic strategies against OTSCC." (PMID 31083515, 2019). "IL-17F mRNA expression was higher in tumor tissue than in non-tumor counterparts." (PMID 28770001, 2017). "Moreover, the lowest ratio of IL-17F/VEGF was found in OSCC patients (P < 0.05): The lower ratio of IL-17F/VEGF correlated to higher tumor stage and lymph node metastases." (PMID 27044404, 2016). "It remains unclear at this point whether the effects of IL-17F on cells in the leukemic microenvironment are capable of mediating tumor-promoting or tumor-suppressing actions." (PMID 26478573, 2015). "In addition, we showed that IL17F and IL23R polymorphisms were positively associated with colon tissue mostly associated to colon location of the tumor." (PMID 26083022, 2015). "Increased levels of IL-17F wereobserved in response to tumor antigens nonetheless." (PMID 23935856, 2013). "Together, our data suggest an involvement of IL-17F in the tumor angiogenesis." (PMID 22509371, 2012).
tumor (continued). "Specifically, mast cells not only secrete mediators related to pro-tumor function such as trypsin-like enzymes, chymotrypsin, vascular endothelial cell growth factor and histamine, but also mediators related to anti-tumor progression such as cystatin C and IL-17F." (PMID 39814702, 2025). "Baseline IL-17f was also one of the 32 cytokines differentially elevated at baseline depending on primary tumor histology, suggesting that the relationship between IL-17 and response might be tumor specific." (PMID 39403930, 2024). "In our results, it is confirmed that the expression of IL-17A, IL-17B, IL-17C, IL-17D, IL-17E (IL-25), and IL-17F in tumor immune subtypes is statistically significant, especially in BRCA; there may be a potential microenvironmental regulation mechanism that remains to be investigated." (PMID 36159856, 2022). "However, IL-17f has an inhibitory effect on tumor angiogenesis." (PMID 32522267, 2020). "In addition, the modulation response of IL17F may inhibit tumor angiogenesis and enhance the inflammatory response of the host to tumorigenesis." (PMID 29511476, 2017). "Moreover, the modulation response of IL-17F may inhibit tumor angiogenesis and enhance the inflammatory response of the host to tumorigenesis." (PMID 26083022, 2015). "Specifically, alterations in cytokines such as IL32, IL22, IL17F, IL17A, IL16, IL15, and HMGB1 can create an immunosuppressive tumor microenvironment in CTCLs to facilitate immune evasion and tumor progression." (PMID 39409988, 2024). "When the host immunity of C57 mice was compromised by knocking down the Ifng gene or the Il17a/Il17f genes in the mice, the growth of EO771 tumor at the primary site accelerated." (PMID 37553342, 2023). "While, the paired analysis showed that expression of IL26, IL17F, KLRB1, CD40LG, JCHAIN, and NFKBIZ were significantly lower in the tumor group, compared with normal tissues." (PMID 35902909, 2022). "attempted to introduce new therapies based on Th17 lymphocytes which produce IL-17A, IL-17F, IL-21, IL-22, IL-26, IL-6, TNF-α and suppress tumour progression through enhanced antitumor immunity in OC." (PMID 34621670, 2021). "For example, IL-17F is involved in mucosal host defence; IL-17E was confirmed to be an amplifier of TH2 immune responses, and IL-17A shows the highest involvement in tumour progression (including CRC), as well as inflammation and autoimmunity." (PMID 32760201, 2020). "In total, 85% of the HCC tumor samples from the HCV group and 62% of the HCC tumor samples from NBNC group were positive for IL-17F staining (p = 0.0002 by Fisher exact test)." (PMID 28770001, 2017). "In the nude mice model, analysis of the tumor sections showed weaker VEGF staining and fewer blood vessels in IL-17F- than mock-transfected HCT116 tumors." (PMID 22509371, 2012). "Meanwhile, enhanced tumor formation of Il-17f−/− mice in AOM-DSS model and reduced tumor growth of IL-17F over-expression cells in nude mice were found in our study." (PMID 22509371, 2012). "Meanwhile, IL-17F was shown to directly inhibit the vascular endothelial cells and decrease the expression of angiogenesis factors including IL-6, IL-8, and VEGF, thus inhibiting tumor angiogenesis and tumor growth." (PMID 39906741, 2024). "Th17 cells are a veritable cytokine factory, producing a range of cytokines and chemokines, including IL-17A, IL-17F, IL-21, IL-22, TNF-α, and CCL20, which modulate the behavior of fibroblasts, endothelial cells, epithelial cells, macrophages, and tumor cells, thereby sculpting the TME." (PMID 39906741, 2024). "The main findings concerning IL-17F protein expression were in OSCC, which showed that IL-17F expression in tumor tissue and patient serum, but not in saliva, was associated with better prognosis." (PMID 35012470, 2022).
tumor (continued). "Increased Th17 lymphocytes concentration, via the secretion of IL-17F cytokine, which activates the MAPK signaling pathway in BC cells, leads to the unregulated expression of the pro-tumor genes, which finally accelerates tumor progression." (PMID 36497282, 2022). "Interestingly, we found their receptors, IL17RA/IL17RC for IL17A/IL17F, IL10RB/IL22RA1 for IL22, and IL20RA/IL10RB for IL26, were upregulated in tumor cell than in normal epithelial cells." (PMID 35999201, 2022). "In addition, numerous studies have found that the characteristic chemokines of Type 17 T cells, such as IL-17A, IL-17F, GM-CSF, and CCL20, recruit T cells, B cells, neutral granulocytes, and macrophages into tumor tissue in various tumor models." (PMID 35459193, 2022). "Tumor-infiltrating T, B, and NK cell levels and plasma concentrations of Th1 (IL-2, IFN-γ, and TNF-α), Th2 (IL-4, IL-5, IL-6, and IL-10), Th9 (IL-9), and Th17 (IL-17A, IL-17F, IL-21, and IL-22) cytokines were evaluated." (PMID 32802733, 2020). "We reached this conclusion by first showing thatthe metastatic 4T1 tumor, but not its non-metastatic 67NR sibling, inducesproduction of pro-osteoclastogenic cytokines, including IL-17F and RANKL byCD4+ T cells." (PMID 23935856, 2013). "IL-17F appears to inhibit the tumor growth much more pronouncedly after an initial period in nude mice, suggesting that IL-17F did not affect the initial stage of tumor development but rather suppressed its progression." (PMID 22509371, 2012). "The authors suggested that IL-17F might reduce VEGF levels, inhibiting tumor angiogenesis." (PMID 35884974, 2022). "Thus, JAK3 promotes survival and proliferation of malignant T cells and expression of proto-oncogenes/oncomiRs and cytokines (IL-5, IL-9, IL-13, IL-17F and LTA), some of which are growth factor to malignant T cells while others modulate the tumour micro-environment (TME) and anti-cancer immunity." (PMID 33466582, 2021). "IL-17F suppressed the progression of transplanted tumor but not the initial development." (PMID 22509371, 2012). "Collectively, we found no major change in the immune cell subsets by IL-17F, suggesting anti-tumor immunity may not significantly contribute to the reduced colon tumorigenesis in our study." (PMID 22509371, 2012). "However, we did not observe a significant correlation between the cytokines IL-17F and IL-22 and tumor purity, which may also be due to the low expression level of these cytokines." (PMID 33102239, 2020). "In the present study, the absence of STAT1 significantly increased the production of Th17 cytokines (IL-17A, IL-17F, and IL-22) but not of TNF-α and IFN-γ, indicating that a lack of STAT1 signaling induces a significant change in the microenvironment that supports inflammation and tumor formation." (PMID 30235866, 2018). "However, we found that IL-17F had no direct effect on the in vitro proliferation of vascular endothelial cells (HUVECs) and decreased VEGF production was only found in vivo in HCT116 tumor but not in vitro." (PMID 22509371, 2012).